INS (insulin)
Diseases named in the same sentence as INS in open-access papers (continued):
Sharing a sentence is not in itself a finding about the gene and the disease.
Insulin resistance (continued). "Moreover, the impact of exogenous insulin and insulin resistance on cognitive function is unclear." (PMID 34577866, 2021). "Thus, markers of insulin resistance at baseline (high levels of BCAAs and their metabolic by‐products and low levels of urea cycle amino acids) predicted changes in TG/HDL and adiponectin associated with increased insulin sensitivity." (PMID 34277974, 2021). "The presentation of both insulin-resistant and insulin-deficient features in SIDRD cluster in East Asians, including Chinese, may be due to the ethnic characteristics of Asians with a lower capacity of insulin secretion and a rapidly increased insulin resistance compared to western populations." (PMID 35154005, 2021). "Also, chronically elevated levels of inflammatory cytokines such as CRP, TNF-a, IL-6, and IL-1b could enhance insulin resistance (IR), disrupt insulin sensitivity, and consequently impair glucose homeostasis resulting in an increase in the risk of T2DM." (PMID 34917685, 2021). "Progressive insulin resistance and the subsequent failure to cope with dietary glucose, i.e., glucose intolerance, mostly reflects the inability of the adipose tissue (AT) and skeletal muscle to sufficiently eliminate circulating glucose in response to insulin." (PMID 34016966, 2021). "In addition, most studies on TB and T2D do not measure fasting insulin levels in patients; therefore, there are few reports in the literature on the association between serum insulin concentrations or insulin resistance and TB disease severity." (PMID 34835407, 2021). "PRRs’ stimulation could regulate the production of lipids such as ceramides and sphingolipids, which stimulate inflammation, inhibiting the capability of saturated fatty acids to induce insulin resistance; many of these pathways can interfere by blocking insulin action." (PMID 34829598, 2021). "However, as we discuss above, omental fat can have more critical roles in developing insulin resistance and this study aims to analyze the insulin- and mTORC2-dependent signaling downstream SGK1 in the omental fat depot, which can be critical to metabolic diseases." (PMID 34956089, 2021). "Overall, this study suggests that the NBT subfraction of the ethanol extract rich in glucosinolates modulates insulin resistance via PI3K/AKT activation in insulin‐resistant HepG2 cells and might exert potentially beneficial effects in improving or treating glucose and lipid metabolic disorders." (PMID 34136157, 2021). "Although the complex interactions between insulin resistance, hyperglycemia and estrogen impairs the endothelial response in females more dramatically than in males 15, as age reduces the benefits of estrogen on insulin-mediated glucose disposal 37 in females, sex differences are reduced." (PMID 34104095, 2021). "It has also been shown that skeletal muscle insulin resistance due to obesity or dietary fatty acids may result from defective mitochondrial oxidation of fatty acids, which could lead to the accumulation of ceramides that may inhibit insulin signalling." (PMID 34684378, 2021). "Interestingly, circulating levels of TNF-α have been shown to be positively correlated to maternal insulin resistance, suggesting that placental EVs may modulate insulin sensitivity during gestation." (PMID 34769262, 2021). "However, the right-shifted concentration–response curve of insulin induced GSK-3 phosphorylation in STZ-treated differentiated cells is suggestive of the development of insulin resistance that was further confirmed by the insulin potentiating effect of exendin-4." (PMID 33616807, 2021). "Therefore, we aim to make rapid insulin resistance by directly exposing excess insulin." (PMID 34358068, 2021). "Therefore, attenuation of insulin resistance in obese Slc16a13 knockout mice could be attributed to improved hepatic insulin sensitivity." (PMID 34211098, 2021).
Insulin resistance (continued). "This does not exclude the possibility of impaired insulin signaling as after 48 h fat infusion we have previously shown impairment of liver Akt phosphorylation associated with hepatic insulin resistance in the absence of changes in serine phosphorylation of IRS." (PMID 34948019, 2021). "However, FM supplementation did not cause significant improvements in the fasting blood insulin secretion, insulin resistance (HOMA-IR), body weight, food intake, and blood triglyceride concentration." (PMID 34072141, 2021). "Although they allow to hypothesize that acute exercise reverts the molecular basis involved in the pathogenesis of insulin resistance, it is noteworthy that the restored insulin sensitivity is not mediated by the improvement of the early steps of the classic insulin signal cascade." (PMID 32737757, 2021). "Thus, the modification of stress-responsive pathways could regulate proximal and distal insulin signaling pathways and subsequently influence insulin resistance in DM progression." (PMID 34885698, 2021). "Furthermore, diets high in fat may promote insulin resistance partially through elevation of free fatty acid (FFAs), which concomitantly impaired insulin signaling." (PMID 34527687, 2021). "Hence chronic exposure to high reactive oxygen species may lead to persistent inflammation and insulin resistance, due to decreased insulin signaling and impaired glucose and lipid metabolism in tissues." (PMID 34299261, 2021). "Moreover, inflammatory markers (interleukin 6, interleukin 1β, and tumor necrosis factor α), insulin sensitivity (fasting glucose, insulin, and homeostatic model assessment for insulin resistance index), and lipid profile (cholesterol, HDL, and LDL) significantly improved after TRE compared with ND." (PMID 34649266, 2021). "In this concept, it was postulated that tissues normally responsive to insulin for glucose uptake (such as muscle and fat cells) are protected from chronic hyperinsulinemia-mediated nutrient excess (intracellular hyperglycemia) due to the development of (hyperinsulinemia-induced) insulin resistance." (PMID 34360563, 2021). "However, as we consider AD and insulin resistance, as well as disease stage, inhibiting just mTORC1 may sufficiently reset insulin sensitivity." (PMID 34215308, 2021). "The development of insulin resistance and T2D has been connected with the expanded release of proinflammatory cytokines, which may impair insulin signaling, and this is supported by a clinical study in which T2D elevated FFAs and IL-1β in plasma, promoting insulin resistance." (PMID 34360006, 2021). "Considering that hyperglycemia and peripheral insulin resistance are common side effects induced by AAPs, a compensatory hyperinsulinemia should be expected regardless, and this makes difficult to establish the direct or indirect effects of AAPs on insulin secretion by the pancreatic β-cells." (PMID 33800403, 2021). "Thus, the simultaneous presence of elevated concentrations of palmitate, insulin, cytokines, and LPS might act in concert to trigger IL-8 production and foster insulin resistance in a vicious feed-forward cycle." (PMID 33919366, 2021). "Likewise, disturbances in the intrauterine environment, such as the intake of a low-protein diet or a high-fat diet during pregnancy, alters their F2 offspring’s birth weight due to alterations in insulin signaling and during adulthood; they present metabolic syndrome or insulin resistance." (PMID 34066827, 2021). "It is important to note that, whereas physiological ROS production may enhance insulin sensitivity in the onset of insulin resistance, long-term ROS overproduction leads to oxidative stress and inflammation, promoting irreversible oxidative damage and subsequent metabolic alterations." (PMID 33557198, 2021).
Insulin resistance (continued). "Reduced correlation of HDL triglycerides and cholesterol in men may reflect the well-known sexual dimorphism of insulin resistance and sensitivity: women show higher insulin sensitivity (hence lower resistance) than men, and this has also been confirmed by studies using animal models." (PMID 34070169, 2021). "In addition, we observed a significant decrease in insulin-induced AKT, p42/44 MAPK and p70S6K phosphorylation in aorta artery and heart from iLIRKO mice compared to control mice at 6 and 12 months of age, demonstrating that hepatic insulin resistance impairs cardiovascular insulin signaling." (PMID 34440804, 2021). "An explanation for this is currently lacking but may possibly reflect a sexual dimorphism in the relationship of these lipidome components and insulin resistance and/or cardiometabolic risk, as previously reported for relationship of TAG and DAG species and hepatic insulin resistance." (PMID 34068687, 2021). "The association between fasting insulin with renal outcomes in diabetic as well as non-diabetic patients has already been observed in previous studies, especially if increased fasting insulin is considered as an early marker of insulin resistance." (PMID 34300354, 2021). "Therefore, oral SS administration could improve glucose metabolism by reducing blood glucose levels, regulating insulin secretion, and relieving insulin resistance in T2D rats." (PMID 34439921, 2021). "Thus, the robust inflammatory response in patients with SARS-CoV-2 could be a significant contributor to their severe insulin resistance, as both of our patients had elevated inflammatory markers that coincided with increasing insulin demands." (PMID 33992101, 2021). "After GH infusion, GH impairs the insulin-elicited suppression of endogenous glucose production, but this effect is not correlated to modifications of hepatic glucose-glucose-6-phosphate cycle activity, which is a marker of insulin resistance in many metabolic disorders." (PMID 34199514, 2021). "Thus, we hypothesized that insulin treatment would upregulate Cav-1 expression in adipose tissue to alleviate insulin resistance." (PMID 34917687, 2021). "Besides, several arachidonic acid metabolites, including PGE2, PGI2, and LXA4, PGE2 and PGI2 can alleviate insulin resistance and improve insulin sensitivity of pancreatic cells; LXA4 can inhibit the production of IL-6, TNF-α, and ROS, thus alleviating inflammation, and has an antidiabetic effect." (PMID 33628839, 2021). "Type 2 diabetic patients have insulin resistance and usually insulin deficiency but may not require insulin injection throughout their lifetime to survive." (PMID 34840987, 2021). "Thus, we hypothesized that long-term exposure to a high dose of insulin treatment could induce insulin resistance." (PMID 34358068, 2021). "This would suggest that P-Rex2 deficiency may not cause bona fide insulin resistance, but rather affects the maintenance of the insulin response." (PMID 33923452, 2021). "Given the intersection between autophagy and insulin signaling in regulating liver metabolism, it is especially compelling to speculate on the potential for changes in autophagy to contribute to the development of insulin resistance in this tissue." (PMID 34336862, 2021). "The synergistic effect of co-administration of Berberine/ Sitagliptin may have a better therapeutic effect, reducing hyperinsulinemia and fasting blood sugar, and improving insulin sensitivity in rats, suggesting a role in improving insulin resistance in NAFLD." (PMID 34094026, 2021). "In addition, impaired insulin secretion and insulin resistance may play an important role in developing the disease." (PMID 34503545, 2021). "However, metabolism-related pathways, including starch and sucrose, glyoxylate and dicarboxylate, glycine, and serine and threonine metabolism, were only enriched among the downregulated proteins, as was insulin resistance and a glucose metabolism-related insulin signaling pathway." (PMID 34803603, 2021).
Insulin resistance (continued). "Normally, insulin lowers blood glucose levels by stimulating peripheral glucose uptake and suppressing hepatic glucose production; however, a dysfunction could conduct to insulin resistance." (PMID 34209800, 2021). "In addition, the decreased level of Dio2-generated T3 might also inhibit the transcription of GLUT4 in insulin-sensitive tissues, such as adipose tissue or skeletal muscle, which could lead to insulin resistance." (PMID 34660805, 2021). "However, there was a significant increase in the circulating concentrations of insulin in the O group that was partially reversed by the administration of vitamin E. The HOMA index indicated insulin resistance in the O dams, which was ameliorated by vitamin E supplementation." (PMID 34439421, 2021). "Related to this, treatment with a BDK inhibitor BT2, which increases BCAA catabolism, restores the decrease in insulin sensitivity normally associated with elevated BCAA/BCKAs, suggesting that increasing BCAA catabolism may help against obesity-induced insulin resistance." (PMID 34354601, 2021). "On the other hand, other studies suggest that accumulation of BCAAs may have a negative effect on insulin sensitivity and can play a causal role in the development of insulin resistance and T2DM." (PMID 34684308, 2021). "Our data showing that depletion of E1α subunit of BCKD in myotubes impaired insulin‐stimulated glucose transport are consistent with these data and suggest that impaired catabolism of BCAA in skeletal muscle, which would lead to the accumulation of BCAA intermediates, can cause insulin resistance." (PMID 33400857, 2021). "Finally, some of the structural changes that result in improved insulin sensitivity consequent to chronic training might be unattainable for individuals most in need of an intervention to combat insulin resistance." (PMID 34386716, 2021). "In addition, it is considered that lipid accumulation, especially ectopic fat deposition, leads to insulin resistance, impairing the lipolytic function of insulin, generating an amount of free fatty acids, and eventually accelerating the occurrence of metabolic diseases." (PMID 33936248, 2021). "Consequently, beta cells compensate for insulin resistance via an increase in insulin production." (PMID 32774471, 2020). "Furthermore, EMP treatment significantly reduced the levels of blood glucose and insulin in serum and improve glucose intolerance and insulin resistance in T2D rats, suggesting that EMP may also have a regulatory effect on hepatic glucose metabolism." (PMID 32256445, 2020). "In addition, genistein increased AMPK activity under both normal and inflammatory conditions; this was shown to contribute to the anti-inflammatory effect of genistein, which led to an improvement in insulin signaling and the amelioration of insulin resistance." (PMID 33255206, 2020). "Finally, we will highlight, whether correcting defects in pathways which maintain [pH]i within the muscle, could alleviate insulin resistance and improve insulin responses during metabolic syndrome." (PMID 32977552, 2020). "Patients with insulin resistance are unable to mount a normal coordinated glucose-lowering response involving suppression of endogenous glucose production, suppression of lipolysis, cellular uptake of available plasma glucose, and net glycogen synthesis at a normal plasma insulin level." (PMID 33234146, 2020). "Consequently, JMJD1C promotes lipogenesis in vivo to increase hepatic and plasma triglyceride levels, showing its role in metabolic adaption for activation of the lipogenic program in response to feeding/insulin, and its contribution to development of hepatosteatosis resulting in insulin resistance." (PMID 32034158, 2020). "Hence, impaired insulin sensitivity, which has a key role in the development of T2DM, results in low OCN levels which lead to low T production in men which in turn is associated with insulin resistance completing the proposed bone-pancreas-gonads loop." (PMID 33537005, 2020).
Insulin resistance (continued). "Therefore, we hypothesize that administration of both GSH+NO or GSNO, in an animal model of sucrose-induced insulin resistance, will restore systemic insulin sensitivity." (PMID 32942712, 2020). "An earlier study showed that insulin and C-peptide levels were increased in obese individuals compared to lean controls and suggested obese subjects have an impaired glucose homeostasis and exhibit prediabetic factors, including hyperinsulinemia, and insulin resistance." (PMID 33042134, 2020). "Furthermore, rhein dramatically decreased the levels of fasting plasma glucose, fasting insulin, homeostasis model assessment-insulin resistance index (HOMA-IR), TG, and TC, while renal tissues were significantly improved compared with those in diabetic rats that did not receive rhein." (PMID 33287318, 2020). "In addition, when insulin resistance is present in tissues, the blood insulin level also increases." (PMID 33312340, 2020). "The lack of significant antidepressant effect from insulin-based medications suggests that insulin resistance may disrupt the first steps of insulin signaling by the insulin receptor, and that approaches that bypass the first steps of insulin signaling might show better results." (PMID 32971941, 2020). "However, it would appear that this effect is not sustained into older age which may limit the potential use of HMB as a nutraceutical for improving insulin sensitivity, as insulin resistance is most prevalent in older age." (PMID 33101462, 2020). "Also, we compared the indices of IR derived from fasting concentrations values [insulin plus glucose and insulin plus triglycerides (TAGs)] such as Homeostasis Model Assessment of Insulin Resistance (HOMA-IR), Quantitative Insulin Sensitivity Check Index (QUICKI), and the McAuley index." (PMID 32849275, 2020). "Together with a potential direct action of fenugreek compounds, the rise in plasma insulin under lactation-specific conditions, i.e., hypo-insulinemia and insulin-resistance in peripheral tissues except mammary gland, could explain the Igf1r, Insr and Ghr overexpression in the mammary gland." (PMID 33081164, 2020). "Thus, in the presence of insulin resistance as in GK rats, the impaired ability of insulin to deactivate FOXO1 may have enhanced fatty acid utilization." (PMID 32612543, 2020). "Our results provided a reciprocal functional interaction among CaMKIV, ER stress, autophagy and insulin signaling in Tun-treated adipocytes, indicating that CaMKIV regulated autophagy may function as an adaptive role in response to ER stress-induced insulin resistance." (PMID 32660483, 2020). "Thus, our study might underestimate the effect between insulin secretion or increase of insulin resistance and mortality among cancer survivors." (PMID 32132977, 2020). "Similarly, the Insulin Resistance Intervention after Stroke (IRIS) trial revealed higher risk of CVD in normal-weight insulin resistant people with MetS, compared with those without MetS." (PMID 32993664, 2020). "In cancer patients with insulin resistance, the elevated levels of circulating insulin accompanied frequently by insulin receptor (IR) overexpression in cancer cells may be associated with atypical stimulation of non-metabolic effects of IR, including cell proliferation, migration, and survival." (PMID 33008076, 2020). "Liver-specific IR knockout (LIRKO) mice showed severe insulin resistance and glucose intolerance with increased hepatic glucose production, impaired glucose utilization in the liver, and abnormal mitochondrial function because of the failure of insulin activity." (PMID 33105604, 2020). "Among possible biological mechanisms allowing starch-related foods to increase RCC risk, a high consumption of bread and pasta could elevate circulating glucose and insulin concentrations, thus promoting glucose intolerance, insulin resistance, and hyperinsulinemia." (PMID 31906594, 2020).